TLR7 (toll like receptor 7)
Diseases named in the same sentence as TLR7 in open-access papers (continued):
Sharing a sentence is not in itself a finding about the gene and the disease.
influenza (continued). "One of these theories suggests that influenza immunization activates Toll-Like-Receptor-7 on cells, thereby impeding replication of single-stranded RNA viruses." (PMID 36897891, 2023). "In other words, TLR7 signaling is known to be activated in influenza infection, and cases of PV developed after severe influenza infection or vaccination have been described." (PMID 36539957, 2023). "GQD has been proposed playing antiviral and immunomodulatory roles against influenza pneumonia by affecting the TLR7 signaling pathway." (PMID 37089926, 2023). "A preclinical study using TLR7 agonists as adjuvants for influenza vaccination showed improved IgG2c (or IgG2a for BALB/c mice) class switching relative to that in nonadjuvanted groups." (PMID 36094090, 2022). "Similar to these adjuvanted vaccines, one dose of influenza mRNA vaccine, which induced TLR7‐mediated adaptive responses, protected aged mice from lethal influenza challenge." (PMID 36056604, 2022). "While mTOR is involved in the TLR9-induced type I interferon signaling pathway, and stimuli such as the TLR7-agonist gardiquimod or Influenza induce early glycolysis in pDCs, the effect of TLR4-ligands on the metabolism of pDCs is not well studied." (PMID 36059475, 2022). "Whole inactivated influenza virus (WIV) contains all influenza components including many B cell epitopes, and studies indicate they can stimulate TLR7 and TLR9." (PMID 36056604, 2022). "In mice, TLR4 and TLR7 worked additively to induce antigen-specific IgG and provided protection against influenza challenges when this combination was used as an adjuvant." (PMID 35746503, 2022). "In contrast to this, the combination of TLR4 and TLR7 agonists reduced mortality and morbidity in mice against virulent challenges of influenza when it was used as an adjuvant with influenza antigens." (PMID 35746503, 2022). "The response of ABC to influenza infection, resulting in iABC, is T cell independent and requires both extrinsic TLR7 and TLR9 signals." (PMID 36056604, 2022). "PRRs sensing viral RNAs, such as RIG-I, TLR3 and TLR7, have emerged as critical intracellular receptors for the innate immunity against influenza infection." (PMID 35503798, 2022). "TLR-7 has been shown to induce a humoral cellular response and long-term memory response in response to the ssRNA-mediate (Influenza and HIV) infection and vaccination." (PMID 34966175, 2021). "Here we have shown that influenza vaccines comprising TLR7/8a‐NPs and HA can be delivered over prolonged time frames within PNP hydrogels, significantly improving humoral immune responses over clinical adjuvants." (PMID 33955657, 2021). "Recent publications have further demonstrated that the combinations of synthesized TLR4, TLR7, and TLR7/8 ligands were potent adjuvants for recombinant influenza HA vaccines in different animal models." (PMID 33430259, 2021). "For example, during influenza infection, viral particles were detected inside platelets where they colocalized with Toll-like receptor 7 (TLR7) in the lysosomes." (PMID 34977191, 2021). "In a first in humans trial we assessed the safety and immunogenicity of a novel nanoparticle Toll-like receptor 7/8 agonist adjuvant (Papaya Mosaic Virus) at different dose levels combined with trivalent influenza vaccine in healthy persons 18–50 years of age." (PMID 32698532, 2020). "We found that lipidated imidazoquinolines TLR7/8 agonists can elicit a Th1-biased influenza specific immune response in mice and when combined with a TLR4 agonist, elicit a Th17 response as well." (PMID 32210973, 2020). "Exogenous administration of IFNλ reduced both proliferation and activation of B cells during stimulation with influenza antigens whereas in vitro administration of IFNλ in conjunction with TLR7 agonists enhanced Ab secretion and proliferation." (PMID 32407154, 2020).
influenza (continued). "Previous work has demonstrated the efficacy of using a TLR4 agonist in combination with a lipidated TLR7/8 agonist or a lipidated TLR7/8 agonist alone in protecting against influenza challenge either in a DMSO, liposome, or emulsion formulation." (PMID 32210973, 2020). "It has been shown for H5N1 influenza vaccines that TLR7 is involved in the generation of an effective adaptive immune response and that TLR7 activation is severely reduced after inactivation of the antigen with formalin or β-propiolactone." (PMID 32580391, 2020). "The presence of influenza led to an increase of C3 in platelet supernatants but only in those with platelet TLR7 expression as assessed by qPCR or antibody staining." (PMID 30992428, 2019). "Since genomic ssRNA that is released from the influenza virion is detected by TLR79, this present study focuses on examining the protective role of a TLR7 agonist against influenza infection." (PMID 30787331, 2019). "Here, the authors show that influenza can be found in human platelets and that platelet engulfment of influenza A results in TLR7-dependent C3 release, which in turn promotes neutrophil-DNA release and formation of platelet-DNA aggregates." (PMID 30992428, 2019). "Our study demonstrates that, during influenza infection, platelets internalize influenza and coordinate a distinct, multifactorial response as a function of their TLR7-mediated C3 release." (PMID 30992428, 2019). "Host innate immunity mediates the first line of defense towards influenza infection and TLR-7 and TLR-3 are the main sensors for influenza viruses, responsible for triggering the host’s innate immune responses in chickens." (PMID 30823888, 2019). "In this study, we sought to evaluate the effect of TLR7 and the complement system on platelets during influenza infection and their possible impact on augmenting thrombosis." (PMID 30992428, 2019). "To assess if influenza and TLR7 can be located in the same platelet, we isolated platelets from an influenza-infected donor and stained for influenza, TLR7, and the lysosomal marker CD63." (PMID 30992428, 2019). "In this study, we show that influenza is found in the circulation where it is engulfed and recognized by platelet-TLR7 leading to complement C3 release." (PMID 30992428, 2019). "Our findings confirm other studies in which pDCs were stimulated with influenza or West Nile Virus (TLR7), R848 (TLR7/8) or CpG (TLR9)." (PMID 31830086, 2019). "Polymorphisms within the TLR7 or IRF7 genes have been associated with disease outcomes in Hepatitis C, Influenza, and HIV." (PMID 31830058, 2019). "In the present study, we have shown that the TLR7 agonist imiquimod significantly modifies the immune system response to influenza." (PMID 30787331, 2019). "During influenza infection, the expressions of TLR-7, RIG-I, and MDA5 were increased in both in vivo and in vitro studies." (PMID 29880757, 2018). "Alveolar macrophages or bone marrow (BM) neutrophils were therefore treated with the TLR7 agonist imiquimod (to mimic influenza in providing the first signal), followed by incubation with ATP (a common DAMP that provides the second signal)." (PMID 29079611, 2018). "The engagement of pDCs in influenza infection, particularly involving TLR7 stimulation, leads not only to induction of type 1 IFNs, Th1 and cytotoxic responses, but also enhances B cell expansion and differentiation into CD27high plasmablasts." (PMID 29552008, 2018). "Plasmacytoid DCs primarily sense ssRNA viruses, including influenza, through the endosomal TLR7/8 pathway." (PMID 29552008, 2018). "Studies have shown that TCMs can play a role in the treatment of influenza by TLR7 mediated MyD88-dependent signaling pathway." (PMID 30151032, 2018). "During infection, some influenza viral particles are degraded by endosomal proteases, releasing the viral genome RNA and initiating TLR7 signaling." (PMID 30151032, 2018).
influenza (continued). "During influenza infection increased TLR7/8/9 expression is known to correlate with elevated production of Th1-related cytokines IFN-γ, CXCL10/IFN-γ induced protein 10 and CXCL9/monokine induced by IFN-γ (MIG)." (PMID 29552008, 2018). "After influenza infection, cells such as AMs that express TLR7 are able to detect single-strand RNA fragments released from viral particles." (PMID 29515589, 2018). "We previously demonstrated that a TLR3 agonist alone induced a protective immune response and, in combination with a TLR7 agonist, achieved immediate and complete protection against lethal influenza infection." (PMID 29445364, 2018). "Work in mice lacking asparagine endopeptidase suggests that peptidase-dependent activation of TLR7 is essential for cross priming of CD8+ T cells in influenza infection." (PMID 29552008, 2018). "Human cell-based MIMIC®-PTE modules were used and were either left untreated or were treated with benchmark influenza vaccine (Fluzone®, 2012–13), the TLR7/8 agonist R848, or 6 increasing concentrations of mRNA vaccine (5–50 μg/106 cells)." (PMID 28049494, 2017). "Imiquimod, a synthetic TLR-7 agonist, can expedite the immune response against influenza virus infection when combined with influenza vaccines." (PMID 26001608, 2015). "To determine the role of TLR7 in cross-presentation of WIV-derived antigens (e.g. epitopes derived from NP), we investigated the capacity of WIV-pulsed bone marrow-derived TLR7−/− DCs to induce in vitro restimulation of influenza-specific CD8+ T cells." (PMID 23658804, 2013). "Our finding that TLR7 activation is critical for the induction of influenza-specific CTL responses by WIV illustrates how a TLR ligand, in this case ssRNA as an intrinsic component of the vaccine itself, can act as an adjuvant." (PMID 23658804, 2013). "Dendritic cells (DCs) from TLR7−/− mice were unable to cross-present WIV-derived antigen to influenza-specific CTLs in vitro." (PMID 23658804, 2013). "Collectively, these data indicate that TLR7 activation is crucial for the induction of influenza-specific CTL activity upon vaccination with WIV." (PMID 23658804, 2013). "Other authors have addressed the role of TLR7 signaling in influenza WIV-induced homosubtypic protection." (PMID 23658804, 2013). "Our findings indicate that TLR7 processing mediated by a protease, asparagynil endopeptidase, is critical for inducing robust anti-influenza immune responses." (PMID 22916010, 2012). "Of interest however, B cell responses to influenza, or immunogens that contain a TLR7 agonist, have been shown to be less dependent on IL-21." (PMID 22792401, 2012). "One important observation gleaned from studies using SV and VSV was that, in contrast to influenza, UV-inactivation of these virions abolished TLR7 activation." (PMID 21994762, 2011). "Influenza infection induces the enzyme that synthesizes PAF,lyso-PAF acetyltransferase, an effect linked to activation of TLR7/8." (PMID 21079759, 2010). "Receptor-mediated entry of whole inactivated influenza vaccines into the target cells can deliver their single-stranded RNA molecules, an activator for toll-like receptor-7 (TLR7), resulting in the induction of Th1 type immune responses." (PMID 19779615, 2009). "TFPI correlated negatively with TLR3 and TLR7 in COVID19 but positively in influenza." (PMID 40825056, 2025). "The absence of these interactions in toddlers may contribute to their poor T-independent (TI) B cell responses, as TLR7 serves as a key innate pattern-recognition receptor for TI influenza antigens." (PMID 41282111, 2025). "Imiquimod, a well-known TLR7 agonist approved for topical treatment of skin lesions, has shown promise as a vaccine adjuvant by enhancing both mucosal and systemic immunity when applied alongside intradermal influenza vaccines." (PMID 41012165, 2025).
influenza (continued). "Immunization with SE(Trojan-TLR7/8a) has been found to elicit sM2HA2-specific humoral and cell-mediated immunity, both locally and systemically, indicating potential protection against lethal influenza infection." (PMID 40562869, 2025). "SE(Trojan-TLR7/8a) demonstrated cross-protection in BALB/c mice against divergent influenza (H1N1, H5N2, H7N3, H9N2, and H3N2) strains via sM2HA2 as the antigen and SARS-CoV-2 (Alpha, Beta, Wuhan, Delta, and Omicron BA.2) variants via spike-stabilized trimers from the BA.2 variant as the antigen." (PMID 40562869, 2025). "Similarly, the delivery of an influenza vaccine candidate adjuvanted with a combined TLR2/TLR7 adjuvant elicited higher immune responses than unadjuvanted formulations." (PMID 40176816, 2025). "We hypothesized that prolonged co-delivery and presentation of the influenza antigen and TLR7/8 agonist using A-SNP as tunable nanoparticles, mirroring the influenza virus-related innate signaling pathways, could elicit strong cellular and humoral immunity." (PMID 38258117, 2024). "Certain viruses, such as influenza mainly activates IRF3 pathway through TLR7 triggering." (PMID 38835761, 2024). "TLR-7 was demonstrated to trigger both a humoral and long-lasting memory response in reaction to ssRNA-mediated infections as well as vaccinations, such as those involving Influenza and HIV." (PMID 38509569, 2024). "They found that the vaccination with a Toll-like receptor 7 (TLR7) agonist nanoparticle adjuvanted influenza subunit vaccine was effective against different influenza strains and in combination with a SARS-CoV-2 subunit vaccine enhanced the immune response against variants of both viruses." (PMID 38668239, 2024). "The potent effect of TLR7-NP on promoting GC responses and increasing the Tfh/Tfr ratio suggests its potential to support more diversified B-cell clones in the GCs to increase the breadth of antibody response against influenza HA." (PMID 36717665, 2023). "Yin-Qiao San may target some elements in the TLR7/MyD88/NF-κB pathway to achieve its therapeutic effects against influenza pneumonia." (PMID 37089926, 2023). "The success of the influenza vaccine prompted us to explore whether TLR7-NP adjuvant could also help increase the breadth of antibody responses against SARS-CoV-2 variants." (PMID 36717665, 2023). "Remarkably, the TLR7-NP-adjuvanted influenza vaccine induced early and markedly improved titres of subdominant HA-stem specific antibodies and generated effective cross-protection against heterologous influenza viral challenge." (PMID 36717665, 2023). "TLR7 is an X-linked gene for which higher levels of expression have been reported in B cells of naive female versus male mice after vaccination with inactivated influenza vaccine, and these higher levels of TLR7 correlated with high levels of antibodies in the female mice." (PMID 36648132, 2023). "Fufang-Yinhua-Jiedu Granules (FFYH) was used to treat influenza, and the antiviral effect may be attributed to the suppression of inflammatory cytokine expression by regulating the TLR7/MyD88/NF-κB signaling pathway." (PMID 35123452, 2022). "In WT mice infected with FM1 influenza strain, FTA may play an anti-influenza effect by downregulating key factors such as TLR7, Myd88 and NF-κB in the TLR7 signaling pathway." (PMID 35733131, 2022). "This is an important finding, as the factors that regulate the quantity and quality of influenza-specific antibodies (e.g., hormones, TLR7) may also regulate the breadth of the antibody response." (PMID 36094090, 2022). "In this work, we have sought to engineer PNP hydrogels to improve humoral immune response to influenza vaccines comprising HA and a potent TLR7/8a adjuvant, (1‐(4‐[aminomethyl]benzyl)‐2‐(ethoxymethyl)‐1H‐imidazo[4,5‐c]quinolin‐4‐amine), which is a derivative of Resiquimod (R848)." (PMID 33955657, 2021).
influenza (continued). "Immune impairment and TLR downregulation can be rescued by TLR7 ligand or the restoration of the intestinal flora, indicating that the intestinal microbiota provides protection against influenza infection by increasing the activity of the Toll-like receptor 7 (TLR7) signalling pathway." (PMID 34054866, 2021). "Taking advantage of the differential use of virus-sensing systems by different cell types, we test the hypothesis that specifically blocking TLR7-dependent, immune cell–produced cytokines reduces influenza-related immunopathology." (PMID 34473195, 2021). "In summary, we conducted a dose-ranging first-in-human study of a novel TLR7 adjuvant derived from a non-pathogenic plant virus (PapMV) co-presented with a seasonal influenza vaccine." (PMID 32698532, 2020). "We conducted a phase 1 trial (NCT02188810), to assess the safety and immunogenicity of a novel nanoparticle Toll-like receptor 7/8 agonist adjuvant (Papaya Mosaic Virus) at different dose levels combined with trivalent influenza vaccine in healthy persons 18–50 years of age." (PMID 32698532, 2020). "The inhibition of coronaviruses by the synergistic effect of this TCM could be similar in action to the inhibition of influenza through triggering of the TLR7 signaling pathway." (PMID 33746739, 2020). "Reduced numbers of pDCs could lead to increased TLR7/8 mediated infections, such as influenza and RSV infection." (PMID 31830086, 2019). "We isolated human platelets from control donors and incubated them with infectious virions of influenza A (WSN/33) for 30 min at three different ratios to establish TLR7-specificity: 1 plaque-forming unit (pfu) or infectious virion to 10, 100, or 1000 platelets." (PMID 30992428, 2019). "Additionally, influenza virions were found in the plasma of TLR7 KO mice implying possible necessity for TLR7 activation during the initial stages of infection." (PMID 30992428, 2019). "The ability of inactivated whole virions to induce TI B cell responses is linked to the presence of single-stranded RNAs that activate B cells via a TLR7-dependent mechanism, hence TLR7/8 agonists should be considered as potential adjuvants for seasonal influenza vaccines." (PMID 31312199, 2019). "We tested whether stimulation of TLR7, the innate influenza sensor could lead to increased expression of TLR9 as it is known that NF-κB activation by TLRs can induce TLR expression." (PMID 30682165, 2019). "Gui Zhi Ma Huang Ge Ban Tang could reduce lung inflammation in mice significantly and elicit an anti-influenza effect by downregulating expression of the key factors of the TLR7 signaling pathway." (PMID 29849712, 2018). "Indeed, TLR7 stimulation has proven critical for isotype class switching in influenza infection and augments antibody secreting cell (ASC) differentiation." (PMID 29552008, 2018). "pDCs are the primary producers of IFN-α upon influenza infection, which is TLR7-mediated." (PMID 30515164, 2018). "Finally, topical application of TLR7 agonists at the time of influenza vaccination has been shown to improve antibody responses to influenza in the elderly." (PMID 27524984, 2016). "TLR7 plays an essential role in inflammatory cytokine activation in granulocyte-macrophage colony-stimulating factor (GM-CSF)-primed murine neutrophils in response to influenza and the R848, as has been shown using TLR7−/− mice." (PMID 25874762, 2015). "TLR7 signaling plays an important role during influenza infection." (PMID 26474053, 2015). "TLR7 dependent MyD88 activation has been reported to accelerate clearance of influenza in mice." (PMID 23483993, 2013). "The lack of protection in TLR7−/− mice was associated with high viral load and a relative paucity of influenza-specific CD8+ cytotoxic T lymphocyte (CTL) responses." (PMID 23658804, 2013). "Therefore, we expected a stronger impact of the TLR-7 agonist imiquimod on the immunogenicity of our influenza subunit vaccine." (PMID 24300513, 2013).